METTL14 (methyltransferase 14, N6-adenosine-methyltransferase non-catalytic subunit)
Diseases named in the same sentence as METTL14 in open-access papers (continued):
Sharing a sentence is not in itself a finding about the gene and the disease.
infection (24 papers, 2017 to 2025). The state of being infected such as from the introduction of a foreign agent such as serum, vaccine, antigenic substance or organism. "Moreover, deletion or mutation of the phosphorylation site on METTL14 impaired the inhibition of ROS level by EsxB and increased bacterial burden or histological damage in the lungs during infection in mice." (PMID 38548762, 2024). "METTL3 or METTL14 were knocked down by siRNA 48 h prior to infection, a time point that led to stable loss of both RNA and protein expression throughout the subsequent infection." (PMID 33243990, 2020). "In this study, we found that infection with H. pylori significantly downregulated METTL14 to promote the progression of GC." (PMID 39827141, 2025). "That study proposed that DDX5 regulates the interaction between METTL3 with its adaptor, METTL14, after infection." (PMID 40214229, 2025). "E. coli F17 infection assays were performed in sheep IECs transfected with Oe-METTL14, pcDNA3.1, si-METTL14, and si-NC." (PMID 41345738, 2025). "Our studies have for the first time established that infection with a virulent strain of CSFV upregulates both METTL14 protein expression and m6A methylation levels in vivo and in vitro." (PMID 38551978, 2024). "Immunofluorescence results revealed that both METTL3 and ALKBH5 aggregated in the cytoplasm following infection (Fig. EV1A,C), while METTL14 remained localized in the nucleus before and after infection (Fig. EV1B)." (PMID 39496835, 2024). "During infection, METTL14 expression is induced, and knockdown of METTL14 leads to decreased latent EBV gene expression." (PMID 37325513, 2023). "In particular, both METTL3 and METTL14 were shown to promote HIV-1 replication in multiple round infection assays and to be required for efficient Gag protein expression in cells transfected with an HIV-1 proviral plasmid." (PMID 35101069, 2022). "METTL3 and METTL14 depletion led to increased expression of the HBc and HBs proteins, consequently promoting the progression of infection." (PMID 33431045, 2021). "The expression of Ifnb1, Il6, and Ifna4 were increased in BMDMs from Mettl14+/− mice after infection with SeV or treatment with 5′‐pppRNA, compared to that in wild‐type BMDMs from Mettl14+/+ littermates." (PMID 34047074, 2021). "We also prepared primary peritoneal macrophages from Mettl14+/+ mice and Mettl14+/− mice followed infection with VSV." (PMID 34047074, 2021). "We further used VSV‐GFP virus to infect HEK293T cells and measured the function of METTL14 on VSV‐GFP infection." (PMID 34047074, 2021). "Upon infection with M. tuberculosis, endogenous p38 was rapidly recruited to METTL14 in primary peritoneal macrophages, indicating a stimulus-dependent interaction between p38 and METTL14." (PMID 38548762, 2024). "Although the intracellular survival of M. tuberculosis markedly decreased in control macrophages that were infected with all these mutant strains, only the lower survival of H37Rv:ΔEsxB was restored in macrophages whose Mettl14 gene was knocked down or knock out at 24 h post infection." (PMID 38548762, 2024). "Under all experimental conditions in Mettl14-intact macrophages, the intracellular survival of the EsxB deletion mutant was significantly lower than that of the WT H37Rv strain, especially up to 6 days post-infection." (PMID 38548762, 2024). "In both METTL3- and METTL14-depleted Caco-2 cells, RNA-sequencing and qRT-PCR revealed upregulated immune response genes following infection (including IL-6, IL-8, CCL20, CXCL1, and CXCL3), while IFN and interferon-stimulated genes (ISGs) remained largely unaffected." (PMID 37509095, 2023). "Overexpression of Flag‐METTL14 decreased IFNB1 mRNA level upon infection with VSV." (PMID 34047074, 2021). "Notably, for Mettl14T72A/T72A mice, at 8 weeks after infection, nearly 50% of mice died, but all the WT mice survived, suggesting that phosphorylation of METTL14 on T72 may promote the anti-TB immunity." (PMID 38548762, 2024).
infection (continued). "Infection of AGS cells with H. pylori at concentrations of MOI = 50, 100 and 150 also significantly downregulated METTL14." (PMID 39827141, 2025). "In keeping with these findings, the mRNA levels of METTL3 & METTL14 (m6A writers), ALKBH5 & FTO (m6A erasers), and YTHDF2 (m6A reader) were significantly increased in a time-dependent fashion in Huh7 cells post SFTSV infection." (PMID 39585899, 2024). "To better understand, the crucial role of METTL14 during SCNT embryo development, we performed lentiviral infection to overexpress porcine METTL14 in pEFs." (PMID 38095020, 2024). "Further confocal fluorescence microscopy analysis of cells infected with CSFV and transfected with pEGFP-METTL14 revealed co-localization of METTL14 and HRD1 around the nucleus upon infection." (PMID 38551978, 2024). "The knockdown of METTL3 or METTL14 using shRNA in MT4 cells and the subsequent infection with the HIV-1 virus (clone LAI) led to a significant decrease in viral replication, as assessed by gp120 mRNA expression and p24 capsid protein levels." (PMID 37509095, 2023). "RT-qPCR was performed on RNA extracted from cells collected at 72 h post infection (hpi), which confirmed effective silencing of METTL3 (75%) and METTL14 (85%)." (PMID 35725909, 2022). "Immunoblotting with antibodies targeting ALKBH5, FTO, METTL14 and METTL3 in ileum tissue from mice infected with RV EW or treated with PBS was carried out at 2 days post infection (dpi)." (PMID 35098923, 2022). "Over the course of infection, levels of the assayed writers (METTL3, METTL14, and WTAP) and readers (YTHDC1, YTHDF1, and YTHDF2) remain unchanged." (PMID 33243990, 2020). "Depletion of METTL3 or METTL14 enhanced ZIKV infection in 293T cells whereas ALKBH5 and, to a lesser extent, FTO knockdown reduced infection." (PMID 29259584, 2017). "H. pylori could significantly downregulate METTL14 when the bacteria had infected AGS cells for 12 h, and the downregulation trend was more significant with a longer infection time." (PMID 39827141, 2025). "We noted a slight decrease in METTL3 and METTL14 protein levels at 36 h post-infection (hpi), whereas the protein levels of FTO and ALKBH5 did not significantly change during CVB3 infection." (PMID 39339923, 2024). "However, METTL3, METTL14, WTAP, ALKBH5, and FTO were all present in both the nucleus and cytoplasm after infection." (PMID 34225491, 2021). "When infected with M. tuberculosis H37Rv, an equivalent expression of Il1b and Il6 was detected in mMettl14f/f and mMettl14−/− at 4 h post-infection, indicating that Mettl14 may not regulate macrophages inflammatory response." (PMID 38548762, 2024). "Recent studies have shown that infections by Human Enterovirus 71 (EV71) and Human Cytomegalovirus (HCMV) lead to a notable upsurge in the expression of METTL3, METTL14, YTHDF1-3, and YTHDC1 in host cells, without affecting the expression of "eraser" proteins." (PMID 38551978, 2024). "The results showed that infections with BVDV, PRV, and JEV did not alter the protein expression of METTL3 or METTL14, indicating that the upregulation of METTL14 protein expression is a specific response to CSFV infection." (PMID 38551978, 2024). "The results showed that the protein levels of METTL3, METTL14, and YTHDF2 did not change significantly in A549 cells during infection by influenza virus WSN/1933." (PMID 35583334, 2022). "Interestingly, infections by other viruses like BVDV, PRV, and JEV did not induce similar changes in METTL14 expression, indicating that it was a specific alteration triggered by CSFV infection." (PMID 38551978, 2024). "Zika virus (ZIKV) replication efficiency was enhanced after METTL3 or METTL14 knockdown, modifying its host mRNA landscape, whereas the hepatitis C virus (HCV) infection rate was increased, not through viral RNA replication but through increased production of infectious viral particles." (PMID 33431045, 2021).
bacterial infection (11 papers, 2022 to 2025). "A recent study demonstrated that myeloid-cell-specific knockout of METTL14 sensitized mice to bacterial infection, highlighting the hematopoietic origin of the hyper-inflammatory response." (PMID 40092485, 2025). "Deletion of METTL14 in myeloid cells exacerbates macrophage responses to acute bacterial infection by targeting SOCS1 in an YTHDF1-dependent m6A manner." (PMID 40092485, 2025). "Our findings showed that METTL14 knockdown in bone marrow cells increased macrophage sensitivity to bacterial infections." (PMID 39980685, 2025). "All these results suggest that DDX5/METTL3/METTL14-mediated m6A modification suppresses the TLR2/4/NF-κB-mediated inflammatory signaling pathway in vivo during bacterial infection." (PMID 38182816, 2024). "We therefore aimed to evaluate the possibility of DDX5 forming a complex with METTL3 and METTL14 during bacterial infection." (PMID 38182816, 2024). "In bacterial infection, Mettl14 depletion blocked m6A methylation of SOCS1, diminishing its RNA stability." (PMID 35598196, 2022). "Mettl14 ablation in myeloid cells contributes to acute bacterial infection in mice by the continuous production of proinflammatory cytokines, which can be rescued by forced expression of Socs 1 in macrophages depleted of Mettl14 or YTHDF1." (PMID 36225914, 2022). "Additionally, a small number of studies have suggest that METTL14 also plays a role in resistance to bacterial infections, although research in this area remains limited." (PMID 41345738, 2025). "In addition, macrophages deficient in METTL14 or YTHDF1 exhibit impaired SOCS1 induction, leading to increased pro-inflammatory cytokine and chemokine production, which exacerbates responses to bacterial infections." (PMID 39686999, 2024). "Therefore, both METTL14 activation and FTO reduction work together to increase m6A levels upon bacterial infection or LPS treatment." (PMID 36864027, 2023). "The increase in METTL14 and the increase in METTL14 mediate the increase in the m6A modification of SOCS1, and the increase in SOCS1 mRNA stability through YTHDF1 is necessary to maintain the negative feedback control of macrophage activation in response to bacterial infection." (PMID 39337381, 2024). "In the absence of bacterial infection, DDX5 forms a complex with METTL3 and METTL14, which regulates target transcripts, including TLR2/4 mRNAs, through m6A modification." (PMID 38182816, 2024). "We discovered that under normal conditions (i.e., without bacterial infection), DDX5 interacts with two known m6A writer proteins, METTL3 and METTL14, to form a ternary m6A writer complex, which recognizes and binds to TLR2/4 mRNAs to introduce m6A modifications." (PMID 38182816, 2024).
cardiovascular diseases (6 papers, 2021 to 2025). "Atherosclerosis, probably the main cause of cardiovasculardiseases, is also affected by the RNA m6A modification.Indeed, METTL14 was found to be upregulated in an endothelial cell-basedTNFα-induced inflammation model." (PMID 36692498, 2023). "In recent years, many studies have revealed the critical roles of m6A methylation in cardiovascular diseases, which were exemplified by abnormal levels of m6A modification as a result of methyltransferases (writer, Mettl3, and Mettl14) and demethylases (eraser, ALKBH5, and FTO)." (PMID 35004673, 2021). "The dynamic changes in the expression and activity levels of METTL3 and METTL14, as well as the m6A demethylase FTO, can serve as potential biomarkers for cardiovascular diseases." (PMID 40005339, 2025). "However, whether METTL14 is involved in cardiovascular diseases, such as DCM are largely unknown." (PMID 35013106, 2022). "Since that time, m6A methylation has been extensively studied, and its functions, mechanisms, and effectors (e.g., METTL3, FTO, METTL14, WTAP, ALKBH5, and YTHDFs) in various diseases, including cardiovascular diseases, have rapidly been investigated." (PMID 34221238, 2021). "METTL3 and METTL14 are known as core components of the methyltransferase complex, with METTL3 functioning as a catalytic subunit, while METTL14 being responsible for substrate recognition, and they play a pivotal role in cardiovascular diseases." (PMID 36093141, 2022).
metabolic disease (6 papers, 2023 to 2025). A congenital disorder (due to inherited enzyme abnormality) or acquired (due to failure of a metabolically important organ) disorder resulting from an abnormal metabolic process. "Aberrant upregulation of METTL14 and m6A resulted in the suppression of hepatic lipolysis, adipose tissue expansion, and metabolic disorders." (PMID 37902450, 2024). "A series of methylases are involved in the development of metabolic diseases; among them, FTO was found to play a pivotal role in promoting disease, YTHDC2 was believed to suppress disease development, while the role of METTL3 and METTL14 in metabolic disease still needs to be further investigated." (PMID 40066222, 2025). "Here, we unveil a previously unrecognized METTL14/METTL3/G6pc mRNA m6A/YTHDF1 and YTHDF3/G6pc biosynthesis/HGP pathway governing HGP in health and metabolic disease." (PMID 40278833, 2025). "Deletion of hepatic Mettl14 decreased HGP and ameliorated HFD‐induced metabolic disorders." (PMID 40278833, 2025).
inflammation (3 papers, 2021 to 2024). Aberrant reaction of the microcirculation characterized by movement of fluid and leukocytes from the blood into extravascular tissues. "To further confirm the expression of METTL14, WTAP, METTL3, FTO and ALKBH5 in NPC tissues, we utilized RT‐qPCR to detect their expression in 28 NPC tissues and 7 nasopharyngeal chronic inflammation tissues." (PMID 39021049, 2024).
retinopathy (3 papers, 2022 to 2025). "Using high-throughput MeRIP-seq and RNA-seq, we investigated the regulation of METTL14-mediated m6A modification in photoreceptors and revealed two potential mechanisms underlying retinopathy in RKO mice." (PMID 35698136, 2022). "Taken together, our findings suggested that ubiquitination of METTL14 promotes retinal neovascularization via m6A-modification on MXD1 mRNA in oxygen induced retinopathy." (PMID 40303324, 2025). "Furthermore, METTL14 conditional knockout (cKO) mice within an oxygen-induced retinopathy (OIR) model showed fewer neovascular formations." (PMID 40303324, 2025).
cardiac diseases (2 papers, 2021 to 2022). "Interestingly, in contrast to the evidence that elevation in m6A levels contributes to cardiac injury in many cardiac diseases, our results demonstrated that Mettl14 protected against cardiac I/R injury by employing gain- and loss-of-functional assay." (PMID 35004673, 2021). "Inhibiting METTL14 might be an effective therapeutic strategy for various heart diseases." (PMID 36351918, 2022).
neurologic disorders (2 papers, 2023 to 2025). "The methyltransferase METTL14, which is critical for m6A modification, has been demonstrated to be significantly involved in neurological disorders." (PMID 41175640, 2025).
adenocarcinoma (1 paper, 2021). A common cancer characterized by the presence of malignant glandular cells.
digestive system tumors (1 paper, 2023). "The RNA methyltransferases associated with ncRNAs in digestive system tumors are METTL3, METTL14, WTAP, and FTO." (PMID 37781524, 2023).
hematopoietic cancer (1 paper, 2021). "Another study demonstrated that SPI1, as a transcriptional factor in hematopoietic cancer cells, could directly suppress the expression of METTL14." (PMID 35003212, 2021).
METTL14 also shares sentences with these, for which no sentence is quoted: nasopharyngeal carcinoma (7 papers); non-small cell lung carcinoma (6); diabetic cardiomyopathy (4); Hyperglycemia (2); injury (2); myelodysplastic neoplasms (2); non-alcohol Fatty Liver Disease (2); preeclampsia (2); pulmonary hypertension (2); sarcoma (2); aneurysm (1); Arthritis (1); bladder (1); bladder urothelial carcinoma (1); Burkitt lymphoma (1); carotid atherosclerosis (1); Cerebral ischemia (1); chronic kidney disease (1); cutaneous melanoma (1); cutaneous squamous cell carcinoma (1); developmental delay (1); digestive system cancer (1); dilated cardiomyopathy (1); embryonal carcinoma (1); endocervical carcinoma (1); endothelial dysfunction (1); Fanconi anemia (1); fibrosis (1); glomerulopathy (1); head and neck cancer (1).
A further 43 diseases each share a sentence with METTL14 in 1 paper.